TNF (tumor necrosis factor)
Diseases named in the same sentence as TNF in open-access papers (continued):
Sharing a sentence is not in itself a finding about the gene and the disease.
bacterial infection (continued). "γδ T cells also produce cytokines IFNγ and TNFα in responses to bacterial infections." (PMID 27560150, 2016). "Although TNF secretion was similar to the control group, IL-6 and IFN-γ production remained low and could possibly explain the susceptibility of SS patients to bacterial infection." (PMID 27780938, 2016). "In addition, Kim and colleagues recently found that tumor necrosis factor (TNF) acts in the brain during bacterial infection to increase adaptive immune responses." (PMID 27065209, 2016). "However, a previous study demonstrated that bone marrow derived macrophages (BMMΦ) infected with BVDV1 in vitro have been shown to secrete less TNFα protein in response to LPS or bacterial infection compared to uninfected BMMΦs." (PMID 27420479, 2016). "TNF-α was also significantly increased in the spleen and head kidney during bacterial infection." (PMID 27706080, 2016). "On the other hand, TipDCs (TNF-alpha/iNOS/NO producers) could be a potential immunotherapeutic target since it has been described that partial blocking of these cells protects against bacterial infections by priming CD8+ killer T cells." (PMID 26484351, 2015). "A similar cytokine profile and outcome with secondary bacterial infections has been described after peritoneal lypopolysaccharide (LPS) challenge in animals previously exposed to peritoneal bacterial products or cytokines such as tumor necrosis factor (TNF)." (PMID 25984763, 2015). "To test whether TNF-α played a role in coinfection, we treated mice in a low-dose coinfection regimen with anti-TNF-α immediately prior to and during secondary bacterial infection (5 and 7 dpi)." (PMID 26265006, 2015). "CMR of C. burnetii can induce nonspecific immunoresponses, producing high levels of interferon-γ (IFN-γ) and tumor necrosis factor-α (TNF-α) in hosts, which inhibit viral, protozoan and bacterial infections via activation of bactericidal systems of macrophages and cytotoxicity of NK cells." (PMID 25909586, 2015). "However, recent studies have identified a subset of DCs, tumor necrosis factor-alpha (TNF-alpha)/inducible nitric oxide synthase- (iNOs-) producing DCs (TipDCs), which has been found in the course of viral or bacterial infections." (PMID 26484351, 2015). "Since TNF-α is part of the normal immune response against bacterial infections, it is necessary to investigate whether the administration of anti-TNF-α mAb might result in an increased risk of bacterial superinfections." (PMID 23527251, 2013). "Interestingly, SIRPα was deglycosylated in monocytes after bacterial infection, whereas under TNFα stimulation and under control conditions only a very slight band of the deglycosylated form was observed." (PMID 23448224, 2013). "In addition, increased TNF-α and IL-6 production can potentiate the severity of combined influenza A virus and bacterial infections." (PMID 24191131, 2013). "Regarding IL-6 and TNF-α serum levels, the data of the present study are in agreement with previous studies, which demonstrated important limitations of these two inflammatory cytokines as biomarkers of bacterial infection." (PMID 23690657, 2013). "TNF is well-known to be required for protection against bacterial infections." (PMID 22848611, 2012). "TNF-α and IL-6 are important for the early innate immune response in bacterial infection." (PMID 21818362, 2011). "Previous, we reported that sB7-H3 was elevated in patients with bacterial infections and its level was correlated with plasma TNF-α, which suggested that B7-H3 might be involved in inflammatory reaction." (PMID 21931843, 2011). "Furthermore, a previous report showed that human PYCARD is required for TNFα and IL-6 expression upon bacterial infection." (PMID 20808838, 2010). "Interestingly, the extend of blood influx induced by TNF-α was lower than the influx observed after bacterial infection." (PMID 19693266, 2009).
bacterial infection (continued). "Interestingly, mice that survive bacterial infections produce less TNF-α and IL-6 cytokines, the important mediators of fatal septic shock." (PMID 17059608, 2006). "Although soluble TNF in controlling intracellular bacterial infections is uncontested, the function of membrane TNF, which is subsequently cleaved by the metalloproteinase-disintegrin TACE (TNFα converting enzyme) into the secreted trimeric TNF, is not established." (PMID 16285886, 2005). "IL-1β, IL-6, IL-18, and tumor necrosis factor (TNF)-α are pro inflammatory cytokines, and procalcitonin (PCT) and C-reactive protein (CRP) are nonspecific markers of systemic inflammation that increase sharply during pathogenic infections including bacterial infections." (PMID 40532039, 2025). "Cytokines, interferon-γ, and tumor necrosis factor (TNF)-α directly influence tight junction function, and also modulate both membrane microdomain localization of tight junction proteins and lipid composition of tight junctions, resulting in bacterial infection and inflammation." (PMID 38962471, 2024). "Besides TNF-α and IL-6, also IL-1β drives protective immunity during bacterial infections." (PMID 38562936, 2024). "Therefore, a combinational challenge using LT + TNF and the conclusions generated using this model could be more relevant to bacterial infection than the treatment of LT or TNF alone." (PMID 37855658, 2024). "In addition, glucocorticoid use showed an increase in the progression of bacterial illnesses, while no increased risk of bacterial infection was observed in patients taking TNF inhibitors." (PMID 37109050, 2023). "Reductions in proinflammatory markers C-Reactive protein (CRP), interleukin – 6 (IL6) and tumor necrosis factor-α (TNFα) and increments in anti-inflammatory markers (interleukin – 4 (IL4)) were associated with an improvement in CSDD and MSEE in patients recovering from a bacterial infection." (PMID 37762523, 2023). "Thus, increasing TNF-α in the early stages of a secondary bacterial infection may improve the migration rate of neutrophils and alleviate symptoms." (PMID 36475755, 2023). "Finally, drug-loaded hydrogels were demonstrated to have remarkable antibacterial and anti-inflammatory activities by their significant (p < 0.05) reduction in both harmful S. aureus bacterial infection and the levels of painful TNF-α, IL-6, and IL-8 pro-inflammatory cytokines." (PMID 35448124, 2022). "Thus, the balance between IL-10 and TNF-α seems to be important for immune homeostasis maintenance, as demonstrated by a curative effect of blocking of the IL-10 pathway in several models of bacterial infections such as from Listeria, Klebsiella, Pseudomonas, Streptococcus, or Mycobacterium." (PMID 31075981, 2019). "During viral or bacterial infections, this cytokine is at the top of the inflammatory cascade, as it is produced primarily by activated lymphocytes and can subsequently activate macrophages, resulting in the secretion of other pro-inflammatory mediators (e.g. TNF-α)." (PMID 30077530, 2018). "SET-M33 is already known to abate TNF-α production in vitro in cells stimulated with LPS from P. aeruginosa and K. pneumoniae, but nothing was published regarding its inhibitory effect on other cytokines and enzymes that together establish inflammatory processes triggered by bacterial infection." (PMID 27758868, 2016). "However, macrophages produce proinflammatory cytokines, such as tumor necrosis factor (TNF), during bacterial infections, and the roles of macrophages and TNF in UTI have so far been unknown." (PMID 26861402, 2016). "Most prominent effects seen in this study are inhibition of phagocytosis and TNF-α production, and since peptide and receptor expression are up-regulated by LPS, these signaling pathways might act as inhibitory feedback mechanisms in bacterial infection." (PMID 27737007, 2016).
bacterial infection (continued). "It was also demonstrated that DEPe suppressed Listeria monocytogenes-induced secretion of IL-12 and TNFα in rat alveolar MΦ and that DEP-enhanced production of IL-10 may also increase the susceptibility of diesel particulate matter-exposed MΦ to bacterial infection." (PMID 25710172, 2015). "Interestingly, compared with controls, piperine-administered mice had significant higher IL-6 and TNF-α levels in their peritoneal cavity lavage fluids at 6 h but had lowered levels of these cytokines at 24 h after bacterial infection, accompanied with a declined bacterial burden at 24 h." (PMID 26439699, 2015). "Interestingly, our data demonstrate a positive correlation of circulating A-FABP with TNF-alpha and procalcitonin, and we believe that bacterial infection might be a more important contributor than stress alone." (PMID 23375099, 2013). "Thus, increased TNF-α in the INV group is likely not due to RSV infection but perhaps a secondary underlying bacterial infection in some of the lambs since the lambs are acquired colostrum-deprived at 1–2 days of age." (PMID 24284879, 2013). "Therefore, cytokines such as TNF-α and IL-6 could work in synergy to maintain olfactory tissue homeostasis while removing the bacterial infection." (PMID 22642871, 2012). "In our investigation, little TNF-α could be detected at 18 hr after bacterial infection." (PMID 17059608, 2006). "We wished to address the question of how bacterial infection of about thirty percent of the host cells could give rise to NF-κB DNA binding activity equivalent to activation of NF-κB in nearly all of the host cells as TNFα treatment of the cells does." (PMID 15324458, 2004). "Significant alterations in the neutrophil proteome were observed as early as 15 min poststimulation with TNF-α, LPS, and PMA, indicating the neutrophils were sensitive and responded rapidly to bacterial infection, proinflammatory cytokine, and PKC activator." (PMID 41033464, 2025). "Administration of the AdipoR1 antibody during bacterial infection impaired the inducible expression of cytotoxic genes Perforin A and Granzyme B and pro-inflammatory cytokines IFN-γ, TNF-α, and IL-6 and reduced the ability of T cells to produce Granzyme B." (PMID 41249580, 2025). "(2012) reported that the concentrations of inflammatory mediators TNF‐α and IFN‐γ increased in response to bacterial infection." (PMID 39792067, 2025). "The TIP peptide, mimicking the lectin-like domain of TNF, directly binds to the α subunit of the epithelial Na+ channel, expressed in both alveolar epithelial and capillary endothelial cells, and may increase lung endothelial barrier function and alveolar fluid clearance during bacterial infection." (PMID 40485585, 2025). "These cells produce key inflammatory cytokines such as tumor necrosis factor (TNF), interleukin 1 (IL‐1), and interleukin 6 (IL‐6) in the early phases of the response to bacterial infection." (PMID 41427018, 2025). "Upon stimulation by bacterial infections or inflammatory cytokines like TNF-α, NF-κB is activated, resulting in the upregulation of proinflammatory genes such as IL-1β, IL-6, and TNF-α." (PMID 40917746, 2025). "Notably, the loss of CaMKKβ activity inhibited the ability of tilapia leukocytes to express Perforin A, Granzyme B, IFN-γ, TNF-α, and IL-6 and reduced the frequency of Granzyme B-producing T cells, consequently impairing the ability to control bacterial infection." (PMID 41249580, 2025). "Following a mixed bacterial infection, the experimental groups showed significantly higher levels of NFκB, TLR4, IL-6, TNF-α, and IL-1β compared to the control group (p < 0.05)." (PMID 40136393, 2025). "It is known that, in patients with bacterial infection, PCT blood levels increase in response to toxins and some cytokines (TNF-α, IL-6, IL-1β), and its level decreases dramatically in parallel with the success of the treatment." (PMID 39797227, 2024).
bacterial infection (continued). "In the process of viral and bacterial infections infection, extrinsic apoptosis initiated by the binding of TNFR-specific ligand TNF-α to cell surface TNFR1 is a way for host cells to clear mycobacterial pathogens." (PMID 39226319, 2024). "In the present study, the investigation into TNF-α and TNF-β expression dynamics across N. Tilapia and E. Sea Bass provides critical insights into interspecies variations in immune responses to bacterial infections." (PMID 39684540, 2024). "Spleen levels of IL-4, TNF-α, and IFN-γ play a vital role in immune regulation, host defense against bacterial pathogens and protection from lethal bacterial infection." (PMID 37779705, 2023). "Second, USP18 can boost the susceptibility of S. aureus by negatively regulating the IFN-I pathway to reduce TNF-α signaling, and inhibition of USP18 can improve the body’s bacterial infection status." (PMID 36189314, 2022). "Constitutively intact NF-κB function in NDAS patient hematopoietic cells or in skin fibroblasts after LPS or TNF signaling may account for the unique phenotype of systemic inflammatory disease without apparent increased susceptibility to viral or bacterial infection found clinically." (PMID 35289316, 2022). "We also observed a similar phenotype for monocytes, where pre-treatment with individual cytokines, especially TNF-α and CX3CL1, showed increased intracellular survival upon bacterial infection." (PMID 35007290, 2022). "In bacterial infection stimulation by proinflammatory cytokines IFN-γ and TNF and granulocyte colony stimulating factor (G-CSF) leads to an upregulation of CD64 expression (5–10-fold in comparison with baseline levels)." (PMID 35345614, 2022). "PCT is synthesized in response to endotoxins or mediators, interleukin (IL)-1β, tumor necrosis factor (TNF)-α, and IL-6, during bacterial infections and has a strong correlation with the severity and extent of bacterial infections." (PMID 35547462, 2022). "As well-known inflammatory cytokines or chemokines, IL-1β, IL-8, IL-6, TNF-α and TLR4 are involved in various types of inflammatory responses, and play key roles in the inflammatory process during bacterial infection of bovine mammary glands." (PMID 36233122, 2022). "Our work shows that during E. coli K1 infection of the brain, astrocytes are activated by microglia-derived TNF-α, which then secrete chemokine CXCL1 to promote neutrophil recruitment, which is required to control bacterial infection." (PMID 35742984, 2022). "The extract can affect the COX-2 pathway by affecting the release levels of TNF-α, IL-6, and PGE2, which are key mediators released by macrophages during bacterial infection, so as to achieve the purpose of anti-inflammatory." (PMID 36234947, 2022). "TNF-α and IFN-γ are abnormally increased in bacterial infections but seem to be more significant biomarkers in Mycobacterium tuberculosis infection." (PMID 35463642, 2022). "Injection of IL-1α, TNFα, OSM, IL-22 and IL-17 together in the wound edges induced delayed wound healing similar to that induced by the bacterial infection." (PMID 36275755, 2022). "Naive CD4+ T cells can be differentiated into Th17 cells that produce IL-17, Th1 cells that produce TNF-α and IFN-γ, and Th2 cells that produce IL-4, and during intracellular bacterial infection." (PMID 35663972, 2022). "Similar findings were observed in the sera levels of IL1-β, TNF-α, and IFN-γ in pigs with viral respiratory disease and in cattle with bacterial infection." (PMID 34944151, 2021). "Second trimester placental explants (16–20 weeks, n = 5/group) were treated with lipopolysaccharide (LPS, to mimic bacterial infection) and ACE2, CCL2, IL-6/8 and TNFα mRNA was assessed." (PMID 34359894, 2021). "Therefore, using TNF antibody may alleviate the inflammation to resist bacterial infections." (PMID 34869718, 2021).
bacterial infection (continued). "Following bacterial infection, BDNF pretreatment reduces the expression of TNF-α, IL-16, IL-1β, and the NFκB pathways, and increases IL-10 and Trk expression." (PMID 34831151, 2021). "Upon bacterial infection of IECs, ALPK1 has been shown to signal through TRIF/TRAF6 to NF-κB, triggering secretion of proinflammatory cytokines like IL8 and TNFα." (PMID 32076438, 2020). "The increased expression of this receptor has been shown to occur following the release of the pro-inflammatory cytokines TNF-α and IFN-γ that are produced in response to viral or bacterial infection." (PMID 32759853, 2020). "Among them, pro-inflammatory cytokines (IL-6, TNF-α) and chemokines (MCP-1, MIP-2) are representative mediators released in response to bacterial infection." (PMID 32153410, 2020). "Canonical NF-κB as prototypic NF-κB signaling is stimulated by various extra- and intracellular stimuli, including tumor necrosis factor alpha (TNF-α), oxidative stress or bacterial infections, and regulates inflammatory responses." (PMID 32912211, 2020). "In intracellular bacterial infections, CD4+ T cells differentiate into T helper type 1 (Th1) effector cells that secrete IFN-γ and TNF; these mediate protection by stimulating the anti-microbial activity of macrophages." (PMID 32411623, 2020). "Several studies have suggested that pre-administration of CpG-DNA within three days before bacterial infection leads to the expression of several cytokines such as IL-6, IL-12, IFN-γ, and TNF-α, which enhances the host defense system." (PMID 31295956, 2019). "Since TNF is a major factor in bacterial clearance, TNF-upregulated DIO3 is a mechanism to fight bacterial infection." (PMID 31519956, 2019). "High levels of proinflammatory cytokines are observed during bacterial infection in CF patients, including IL-8 (a human analog of CXCL2 in mouse) and TNF-α." (PMID 29755959, 2018). "Bone-resorbing cytokines such as IL-1β, TNF-α, IL-6, and RANKL are produced in reaction to bacterial infections and induce ABL." (PMID 29670725, 2018). "In order to mimic inflammatory conditions similar to bacterial infection or DED, we challenged rhu-pGSN stimulated HCE cells with the bacterial toxin LPS and the inflammatory cytokine TNFα." (PMID 30177722, 2018). "If bacterial infection occurred during HDM allergen sensitization, the allergic airway response was exacerbated, particularly by the expansion of Th17 cells and increased TNF-α levels." (PMID 29184554, 2017). "Among many miRNAs, the role of miR-155 is to upregulate proinflammatory cytokines, including TNF-α and IL6, in response to bacterial infection and chronic inflammation." (PMID 28507412, 2017). "Pharmacological inhibition of c-Kit results in increased activation of NF-κB in HEK293 cells and secretion of TNFα in dendritic cells and the THP-1 monocytic cell line in response to bacterial infection." (PMID 28626608, 2017). "Classical type 1 cytokines and chemokines (e.g., IL-2, IL-12, IFN-γ, TNF-α, MCP-1/CCL2, MIP-1α/CCL3, and RANTES/CCL5) were predominantly induced around the peak of bacterial infection, and then decreased as bacterial replication was controlled at 28 dpi." (PMID 27479584, 2016). "In particular, neutrophils are prominent in cellular infiltrates and increased pro-inflammatory cytokines (e.g. IL-8, TNFα, IFNγ and MCP-1) are a feature of acute exacerbations in asthmatic patients following viral and bacterial infections." (PMID 27657907, 2016). "Comparable results regarding such high levels of IL1-β, TNF-α and IFN-γ were detected in pigs with viral respiratory disease and cattle with bacterial infection." (PMID 27547520, 2016). "Conversely, IL-4 DCs responded more to molecules involved in bacterial infection, such as flagellin (s=0.27), MDP (s=0.14), TNFα (s=0.39) or IL-1β (s=0.45)." (PMID 25335753, 2014).